RNU6-871P (RNA, U6 small nuclear 871, pseudogene)
Gene: Small nuclear RNA gene on chromosome 12 (59,450,673 to 59,450,772, reverse strand). Ensembl gene ENSG00000251931.
Homologues: Orthologues: chimpanzee U6 (99% identical), dog U6 (59% identical), mouse Gm23185 (55% identical). Paralogues in human: RNU6-164P (67% identical), RNU6-347P (67% identical), RNU6-529P (66% identical), RNU6-1011P (65% identical), RNU6-1124P (65% identical), RNU6-338P (65% identical), RNU6-481P (65% identical), RNU6-716P (65% identical), RNU6-1131P (64% identical), RNU6-1186P (64% identical), RNU6-242P (64% identical), RNU6-333P (64% identical), and 1283 more.